CLU (clusterin)
Diseases named in the same sentence as CLU in open-access papers (continued):
Sharing a sentence is not in itself a finding about the gene and the disease.
lung carcinoma (continued). "The data show that the level of clusterin in lung cancer patient is higher than the level of clusterin in normal control (603.7 / 288.8, p < 0.0001)." (PMID 28954633, 2017). "In the current study, we also analyzed clusterin expression and clinicopathological data in lung cancer." (PMID 28954633, 2017). "On the other hand, data show that the level of clusterin in lung cancer patient is significantly higher than normal control, with acceptable sensitivity and specificity, which indicate that clusterin is a potential new biomarker of NSCLC." (PMID 28954633, 2017). "Studies performed in lung cancer cell lines and animal models showed that clusterin is upregulated after exposure to chemo- and radiotherapy." (PMID 25884382, 2015). "These experimental data support the development of targeted strategies employing clusterin siRNA complementary to conventional cytotoxic therapies for advanced lung cancer." (PMID 25884382, 2015). "The current study investigated the significance of clusterin (sCLU) silencing on DDP chemosensitivity in lung cancer cell lines and investigated the molecular mechanisms underlying the effect of sCLU silencing in vivo." (PMID 25884382, 2015). "Several in vitro studies have examined the role of clusterin in carcinogenesis, lung cancer progression, and response to chemo- and radiotherapy." (PMID 25884382, 2015). "We have shown secreted clusterin (sCLU) silencing directed against sCLU mRNA in sCLU-rich lung cancer cell lines sensitized cells to DDP chemotherapy in vitro." (PMID 25884382, 2015). "The current study investigated the significance of clusterin (sCLU) silencing on DDP chemosensitivity in lung cancer cell lines in vivo and investigated the molecular mechanisms underlying the effect of sCLU silencing." (PMID 25884382, 2015). "On the other hand, in an in vitro study of nonsmall-cell lung cancer cell lines, clusterin overexpression was found to reduce chemosensitivity but indicated a favorable prognosis due to the inhibition of tumor cell migration." (PMID 22799602, 2012). "Consistent with the tissues, the mRNA level of CLU was lower in lung cancer cell lines." (PMID 35270630, 2022). "Our work demonstrates an anti-metastatic role for CLU through a new pathway in lung cancer." (PMID 35626071, 2022). "CLU has a tumor-suppressing effect on lung cancer; similarly, our findings suggest that decreased CLU gene expression may contribute to a worse prognosis in lung cancer patients." (PMID 36685863, 2022). "In this paper, we determine that CLU, especially its precursor form that is downregulated in lung cancer, functions as a tumor suppressor by inhibiting the migration, invasion and metastasis of lung cancer cells." (PMID 35626071, 2022). "Moreover, overexpressing CLU, especially cytoplasmic CLU potently inhibits the migration, invasion and metastasis of lung cancer cells, whereas silencing CLU promotes these phenomena." (PMID 35626071, 2022). "Similarly, in the TCGA lung cancer database, CLU expression in lung tumor tissues was significantly downregulated compared to those in paired normal lung tissues from 34 LUAD and 49 LUSC patients." (PMID 35626071, 2022). "Based on CRISPR library screening, CLU is identified as a tumor suppressor in lung cancer." (PMID 35626071, 2022). "Cytoplasmic CLU is downregulated in lung cancer and correlates with poor survival." (PMID 35626071, 2022). "Importantly, we show that a significant portion of Kras mutation positive NSCLC patients are concurrently deficient of CLU and that TAK1 kinase inhibitor synergizes with existing drugs to treat this portion of lung cancers patients." (PMID 33052230, 2020). "These in vitro data strongly argued that CLU was a potent TSG in lung cancer." (PMID 33052230, 2020). "In short, here we identified CLU as a potent TSG in lung cancer." (PMID 33052230, 2020). "Both tumor promoting or suppressing function have been reported for CLU in lung cancer 26-28." (PMID 33052230, 2020).
lung carcinoma (continued). "It, therefore, remains to be clarified CLU's role in lung cancer." (PMID 33052230, 2020). "Most strikingly, treatment data on cell line, xenograft tumor, and autochthonous lung cancer in transgenic mouse models showed that combinational inhibition of TAK1 and MEK1/2 effectively shrank lung cancer concurrently positive for KRAS mutation and CLU deficiency." (PMID 33052230, 2020). "To find out clinical evidence for CLU as a TSG in lung cancer, we compared CLU expression level in lung adenocarcinoma against para-tumoral tissues using GEO data sets (GSE10072 and GSE7670) downloaded from NCBI GEO database and found significantly lower levels of CLU in NSCLS tissues." (PMID 33052230, 2020). "In case of CLU inactivation, lung cancer cells become uniquely sensitive to TAK1/NF-κB inhibition." (PMID 33052230, 2020). "To test whether this was also true in lung cancer cells, we generated H460 for Dox inducible expression of Clusterin (designated H460-tet-CLU) and found that CLU expression effectively inhibited recruitment of TRAF6 by TGFBR1." (PMID 33052230, 2020). "Furthermore, by secretome analysis and validation experiments, clusterin (CLU) was found as a key regulator for the chemotaxis of E. coli in targeting lung cancer." (PMID 29686328, 2018). "In addition, we examined the correlation between clusterin and clinicopathological features of lung cancer." (PMID 28954633, 2017). "So clusterin show contrary expression profile in two categories of lung cancer." (PMID 28954633, 2017). "As a result, we conclude that the level of serum clusterin in lung cancer have no significance correlation with malignance associate clinicopathological data (although the level of serum clusterin have significance difference between TNM stages, p = 0.0013)." (PMID 28954633, 2017). "In vitro, clusterin silencing by antisense oligonucleotides (ASO) and small-interfering RNAs (siRNA) directed against clusterin mRNA in clusterin-rich lung cancer cell lines sensitized cells to chemotherapy and radiotherapy and decreased their metastatic potential." (PMID 25884382, 2015). "Based on the in vitro experiment of clusterin in the cisplatin resistance of lung cancers, we further examined if clusterin expression affects the cisplatin sensitivity in vivo; A549, A549/sCLU, and A549/pcDNA3.1 cells were injected subcutaneously into the right flank of nude mice." (PMID 25884382, 2015). "Patients with clusterin-positive lung cancer have enhanced disease-free survival." (PMID 21464964, 2011). "Similarly, immunohistochemistry staining results also showed CLU was highly expressed in vessel cells (including endothelial cells and smooth muscle cells) in lung cancer tissues which suggested that CLU might involve in tumor angiogenesis." (PMID 29296216, 2017). "Furthermore, the level of clusterin in serum could be a potential biomarker of lung cancer (its ROC area = 0.8442)." (PMID 28954633, 2017). "Furthermore, we demonstrated that the level of clusterin in serum could be a potential biomarker in lung cancer." (PMID 28954633, 2017). "In a previous analysis using a lung cancer cell line model, we have found that therapies directed against secreted clusterin (sCLU) and its downstream signaling targets pAkt and pERK1/2 may have the potential to enhance the efficacy of cisplatin (DDP)-based chemotherapy in vitro." (PMID 25884382, 2015). "To validate the tumor-suppressive role of CLU, we first analyzed the clinical relevance of CLU expression using GEPIA and TCGA lung cancer databases." (PMID 35626071, 2022). "Recently, using 2D-DIGE, we identified several proteoforms of blood plasma proteins from lung cancer patients, including proapolipoprotein, apolipoprotein AIV, clusterin, gelsolin, fibrinogen, haptoglobin, hemopexin, transferrin, and serotransferrin." (PMID 35512017, 2022).
lung carcinoma (continued). "At the molecular level, the cytoplasmic precursor CLU binds ROCK1 to abrogate the interaction between ROCK1 and ERK and impair ERK activity, leading to the suppression of lung cancer metastasis." (PMID 35626071, 2022). "Taken together, our data strongly argued that CLU was a clinically relevant and essential TSG in lung cancer." (PMID 33052230, 2020). "Of note, in vitro and in vivo tumor suppressive functions of CLU were also confirmed on lung cancers driven by two other important oncoproteins, namely mutant EGFR driven and EML4-ALK driven lung cancers." (PMID 33052230, 2020). "In our previous systemic in vivo screening of lung cancer TSGs, we noticed that somatic knockout of CLU in pulmonary epithelia promoted lung cancer development, suggesting CLU to be a TSG in lung cancer." (PMID 33052230, 2020). "Intriguingly, platelet factor 4 (PF4), an endocrine factor with overexpression correlating with decreased overall survival of patients with lung cancer, emerged as a central node connected with high confidence to SRGN, SPARC, CLU and CCL5." (PMID 31215484, 2019). "We next validated expression level of tumor tissues from lung cancer patients for CLSTN1, CLU and NGAL with immunohistochemistry staining." (PMID 29296216, 2017). "Taken together, CLSTN1, CLU and NGAL were all highly expressed in lung cancer biopsy samples compared with normal tissues." (PMID 29296216, 2017). "The mean intensity±SD for CLSTN1, CLU and NGAL in lung cancer patients were 82.4±17.2, 110.5±23.8 and 63.5±17.7, whereas in healthy controls, the intensity was 11.3±4.1, 49.2±17.6 and 35.5±5.3, respectively." (PMID 29296216, 2017). "Moreover, our current study reveals that cytoplasmic precursor CLU binds ROCK1 to abrogate the interaction between ROCK1 and ERK, leading to the suppression of lung cancer migration and invasion." (PMID 35626071, 2022). "Collectively, these results suggest that CLU is able to bind ROCK1 to block the ROCK1/ERK axis and inactivates ERK1/2 activity, leading to the potent suppression of migration, invasion and metastasis in lung cancer." (PMID 35626071, 2022). "Proximity ligation assay (PLA) also detected the mutual interaction between CLU and ROCK1 in the cytoplasm of lung cancer cells, indicating that cytoplasmic CLU might function by regulating ROCK1." (PMID 35626071, 2022). "We identified that CSTN1, CLU and NGAL are candidate biomarkers for lung adenocarcinoma and may be fertile recourses of mining lung cancer research." (PMID 29296216, 2017). "In this case, the resected specimen was clusterin-negative, and the patient survived 57 months after surgery to succumb to nonsmall-cell lung cancer." (PMID 22799602, 2012). "Nevertheless, in the TCGA-LUAD/LUSC cohort, we could not examine the correlation between CLU expression and the survival prognosis of lung cancer patients, which might be due to various data processing or revised survival information." (PMID 36685863, 2022).
ovarian carcinoma (26 papers, 2007 to 2025). A malignant neoplasm originating from the surface ovarian epithelium. "Our results also support that clusterin is a stress-associated anti-apoptotic protein that is up-regulated in an adaptive cell survival manner following various cell death trigger in ovarian cancer cells." (PMID 26293319, 2015). "CLU expression was associated with survival of patients with primary ovarian cancer (relative risk for overall survival 1.69; 95% confidence interval, 1.52 to 1.95 (P = 0.033))." (PMID 22185350, 2011). "In a previous analysis on the patients with ovarian cancers, we have found that clusterin is a biomarker associated with ovarian cancer in vivo and may be a prognostic factor associated with adverse outcome." (PMID 26293319, 2015). "Here, we explored the effect of lentivirus-mediated shRNA interference of clusterin, investigated whether clusterin was associated with adverse outcome of ovarian cancer cells in vitro." (PMID 26293319, 2015). "CLU is a driving force of tumorigenesis or overexpressed after chemotherapy in ovarian cancer; however, its roles remain controversial for some cancer cells." (PMID 40507922, 2025). "In conclusion, circ_0063804 enhances cisplatin resistance in ovarian cancer via targeting miR-1276/CLU axis." (PMID 38152652, 2023). "This coincides with our observation that Clusterin was significantly increased in the plasma of ovarian cancer patients with chemotherapy-resistant." (PMID 30917846, 2019). "Taken together, these data strongly suggest CLU not only as a biomarker for OC prognosis but also as predictor of chemotherapy resistance in ovarian cancer." (PMID 31540420, 2019). "Increased expression of secreted Clusterin not only inhibited cell apoptosis and induced chemotherapy resistance, but also promoted the deterioration and progression of ovarian cancer cells." (PMID 30917846, 2019). "We found that Transthyretin was downregulated while Clusterin was upregulated in the plasma of chemotherapy-resistant ovarian cancer patients." (PMID 30917846, 2019). "In the current review, we shed light on the diverse roles of HSPs as well as related chaperone proteins like CLU in the pathogenesis of ovarian cancer and elucidate their potential as effective drug targets." (PMID 31540420, 2019). "On the other hand, secreted clusterin has been identified as a predictor for recurrence in ovarian cancer due to its up-regulated expression in chemo-resistant tissue." (PMID 29296216, 2017). "Previous research reveal clusterin was up-regulated in the ovarian cancer cells and the overexpression of clusterin did affect the tumorigenesis of the tumor." (PMID 26293319, 2015). "In summary, present study demonstrated that the biogenesis of ovarian cancer cells was changed following the silence of clusterin." (PMID 26293319, 2015). "In the preset study, we have showed that clusterin express highly in two ovarian cancer cell lines in vitro, while there is lower clusterin expression in the normal ovarian cells." (PMID 26293319, 2015). "Our previous studies suggested clusterin was probably another gene relevant to the treatment of ovarian cancer." (PMID 26293319, 2015). "And the proliferation, clonability, migration, invasion and cell cycle of ovarian cancer cells are significantly correlated with the expression of clusterin." (PMID 26293319, 2015). "To further study the function of clusterin, we silented the clusterin gene of ovarian cancer cells with the lentivirus vector in vitro and detected the clusterin gene expression in silenced-tumor cells." (PMID 26293319, 2015). "In ovarian carcinoma, clusterin overexpression has been shown to be correlated with tumor aggressiveness and/or to be a prognostic factor." (PMID 22799602, 2012). "In ovarian cancer, very limited number of studies has directly examined the effect of altering CLU expression on cell death and survival." (PMID 22185350, 2011).
ovarian carcinoma (continued). "Cell viability assay, FACS analysis and annexin V staining demonstrated that targeting CLU expression by siRNA or OGX-011 sensitized ovarian cancer cells to TX." (PMID 22185350, 2011). "We analyzed prognostic significance of CLU expression in another 47 ovarian cancer tissue samples by immunohistochemistry." (PMID 22185350, 2011). "In a pilot experiment to check the relationship between CLU overexpression and chemoresistance in clinical samples from ovarian cancer patients, we performed immunohistochemistry using CLU Ab." (PMID 22185350, 2011). "To assess any relationship between CLU expression and clincopathological characteristics of ovarian cancer, we used ovarian cancer tissue specimens from 47 patients with early-stage ovarian cancer." (PMID 22185350, 2011). "Immunohistochemical analysis of CLU expression in primary ovarian cancer tissue specimens and their recurrent counterparts from same patients demonstrated higher expression of CLU in the recurrent resistant tumors compared with their primary tumors." (PMID 22185350, 2011). "Cellular viability assay, FACS analysis and annexin V staining were used to evaluate the comparative effect of CLU knocking down in ovarian cancer cells." (PMID 22185350, 2011). "Secretory CLU (s-CLU; 60 KDa) expression was upregulated in TX-resistant ovarian cancer cells compared to parental cells." (PMID 22185350, 2011). "In the present study, we have shown that CLU expression is a prognosticator for ovarian cancer patients who were treated with primary complete surgical staging and adjuvant taxane/platinum combination chemotherapy in early-stage disease." (PMID 22185350, 2011). "Importantly, our results support the idea that, s-CLU is a stress-associated cytoprotective protein that is up-regulated in an adaptive cell survival manner following various cell death trigger including chemotherapy in ovarian cancer cells as well as in most cancer cells." (PMID 22185350, 2011). "Immunohistochemical detection of overexpression of CLU in early-stage (stage I/II) ovarian cancer tissues was significantly related to poor survival, while none of other clinicopathological factors analyzed were related to survival." (PMID 22185350, 2011). "To establish the clinical significance of CLU as a potential molecular target to predict survival in ovarian cancer patients, we conducted this study." (PMID 22185350, 2011). "Overexpression of CLU was found in human ovarian carcinoma and was correlated with impairedsurvival." (PMID 21179408, 2010). "Our data also emphasized the expression of CLU in the malignant tissues of all ovarian carcinoma patients analyzed." (PMID 18637207, 2008). "In both subtypes of the ovarian carcinoma patients, three additional clusters of proteins including CLU, cleaved β chains of HAP (HAPc) and a different cluster of AATf spots were detected." (PMID 18637207, 2008). "In the case of ovarian carcinoma, this explicitly involved elevated levels of CLU in both the EOCa and GOCa patients and enhanced expression of ACT only in patients with EOCa." (PMID 18637207, 2008). "The expression of CPL and CLU was positively-stained consistently in all ovarian carcinoma tissues that were studied." (PMID 18637207, 2008). "CLU has been mentioned as a novel biomarker in ovarian cancer research." (PMID 39031722, 2024). "CLU was found to be a target of miR-1276 and was increased in ovarian cancer patients." (PMID 38152652, 2023). "For instance, in ovarian cancer cells, the nuclear form of clusterin (nCLU) has been found to delay cellular growth and promote apoptosis, while its secreted form (sCLU) exhibits anti-apoptotic potential and consequently accounts for the emergence of chemoresistant and aggressive phenotype." (PMID 31540420, 2019).